ZNF23 (zinc finger protein 23)
Description:
May be involved in transcriptional regulation. May have a role in embryonic development.
Synonyms: KOX16; ZNF359; ZNF612; Zfp612
Tractability: PROTAC: UniProt records ubiquitination sites on it; ubiquitination databases record sites on it.
Gene: Protein-coding gene on chromosome 16 (71,447,597 to 71,463,095, reverse strand). Ensembl gene ENSG00000167377.
Subcellular location: Nucleus
Subcellular location (Human Protein Atlas): Cytosol
Pathways (Reactome):
Gene expression (Transcription): Generic Transcription Pathway
Gene Ontology:
Molecular function: protein binding; sequence-specific double-stranded DNA binding; DNA-binding transcription factor activity, RNA polymerase II-specific; RNA polymerase II cis-regulatory region sequence-specific DNA binding
Biological process: regulation of transcription by RNA polymerase II; regulation of DNA-templated transcription
Cellular component: nucleus
Genetic constraint (gnomAD): Loss-of-function variants: 40 observed, 52.57 expected, observed/expected ratio (o/e) 0.76, 90% interval 0.59 to 0.99. The upper end of that interval is the gene's LOEUF score, 0.99, which puts it in group 4 of 6, group 1 being the genes least tolerant of losing a copy. Missense variants: 769 observed, 818.34 expected, observed/expected ratio (o/e) 0.94, 90% interval 0.88 to 1. Synonymous variants: 253 observed, 284.87 expected, observed/expected ratio (o/e) 0.89, 90% interval 0.8 to 0.99.
Homologues: Orthologues: macaque ZNF23 (97% identical), chimpanzee ZNF23 (93% identical), dog ZNF23 (88% identical), pig ZNF23 (82% identical), guinea pig ZNF23 (78% identical), mouse Zfp612 (75% identical), rat Zfp612 (75% identical), rabbit ZNF23 (71% identical). Paralogues in human: ZNF546 (42% identical), ZNF30 (40% identical), ZNF841 (40% identical), ZNF836 (39% identical), ZNF540 (39% identical), ZNF616 (37% identical), ZNF571 (37% identical), ZNF267 (37% identical), ZNF568 (37% identical), ZNF658 (37% identical), ZNF528 (36% identical), ZNF573 (36% identical), and 164 more.
Diseases named in the same sentence as ZNF23 in open-access papers:
ZNF23 is named in the same sentence as 9 diseases in open-access papers, as found by Europe PMC text mining. Sharing a sentence is not in itself a finding about the gene and the disease. The quoted sentences say what the papers report.
ovarian carcinoma (3 papers, 2014 to 2024). A malignant neoplasm originating from the surface ovarian epithelium. "Increased expression of the ZNF23 has been found to induce apoptosis in ovarian cancer cell lines." (PMID 25018881, 2014).
breast carcinoma (1 paper, 2015).
liver cancer (1 paper, 2021). An epithelial or non-epithelial malignant neoplasm that arises from the liver. "Cisplatin-treatment-induced ZNF23 in a dose-dependent manner in liver cancer that usually retains lowered ZNF23 expression." (PMID 33672287, 2021).
melanoma (1 paper, 2021). A malignant, usually aggressive tumor composed of atypical, neoplastic melanocytes. "ZNF23 was found to be downregulated in hepatocellular carcinoma, ovarian cancer, endometrial cancer, melanoma, as well as in various tumor cell lines (endometrial, liver, glia, neuroblast, ovary) as compared to normal controls." (PMID 33672287, 2021).
thyroid cancer (1 paper, 2017). "ZNF23 has previously been implicated in human cancer, although no mechanistic data yet links it specifically to thyroid cancer." (PMID 28884020, 2017).
cancer (7 papers, 2012 to 2025). A tumor composed of atypical neoplastic, often pleomorphic cells that invade other tissues. "Provided that ZNF23 is a gene downregulated in cancer and associated to inhibition of cell-cycle progression, the identified feedback loop could potentially contribute to an enhanced cellular proliferation and potentially an increased cancer risk." (PMID 35061909, 2022). "For example, ZNF23 inhibits tumor cell growth through enhancement of p27/kip-1 expression, and the expression levels of ZNF23 protein are greatly reduced in human cancer." (PMID 24236047, 2013). "ZNF23, which we discovered was also recruited into the inclusion lumen, has been shown to down-regulate the level of the Bcl-XL protein in some cancer cells." (PMID 22590624, 2012). "ZNF23, a KRAB-containing protein, is down-regulated in human cancers and inhibits cell cycle progression." (PMID 33916522, 2021).
tumor (3 papers, 2013 to 2025). "The clinicopathological analysis in cutaneous melanoma showed that low ZNF23 expression correlates with poor prognostic factors, such as higher tumor thickness, lymph node metastasis, and shorter overall survival." (PMID 33672287, 2021).
ZNF23 also shares sentences with these, for which no sentence is quoted: infection (2 papers); cervical cancer (1).